NLRP3 (NLR family pyrin domain containing 3)
Diseases named in the same sentence as NLRP3 in open-access papers (continued):
Sharing a sentence is not in itself a finding about the gene and the disease.
Anxiety (continued). "It is evident that CA activates the prefrontal cortex FXR and dynamically balances anxiety via the NLRP3 inflammasome/AMPARs signaling pathway." (PMID 38075046, 2023). "The rats treated with MLT eliminated the effects of NP, as the reduced pain severity, improved anxiety- and depressive-like behaviors, ameliorated NF-κB/NLRP3 inflammasome pathways, and modulated levels of cytokines in the HC and PFC." (PMID 36747075, 2023). "Further analysis revealed a positive correlation between the reduction of NLRP3/IL-1β mRNA and amelioration in anxiety in the OFT and EPM tests." (PMID 37047351, 2023). "In this study, we examined aging-related anxiety, social behavior, memory formation, and memory retrieval in WT and NLRP3 KO mice." (PMID 38068904, 2023). "NLRP3 is an inflammasome sensor protein that aggravates anxiety-like behavior by inducing the activation of microglia in PFC." (PMID 38075046, 2023). "NLRP3 inflammasome activation and its correlation with anxiety behavior were analyzed to further investigate the possible anti-anxiety mechanism of VWR following TBI." (PMID 37047351, 2023). "Their impact on the anxiety- and depressive-like comportments and the expression of the inflammasome NLRP3, Nrf2, and some antioxidant enzymes in the dorsal root ganglia (DRG) and amygdala (AMG) were also investigated." (PMID 37891937, 2023). "In conclusion, our findings indicate that under CMS status, the antidepressant clomipramine was capable of improving depressive- and anxiety-like behavior, neuroinflammation, as well as the expression of NLRP3 inflammasome." (PMID 35688836, 2022). "In the present study, we aimed to define the role of the NLRP3 inflammasome in regulating alcohol intake and anxiety-like behavior." (PMID 36539796, 2022). "Taken together, these findings demonstrate that NLRP3 inflammation affects alcohol intake and anxiety-like behaviors, providing an anti-inflammatory target to treat alcohol use disorders." (PMID 36539796, 2022). "A new study has found that injection of flavanol-rich dietary preparation (FDP) to mice following persistent SD exposure results in anti-anxiety activity by pharmacological inhibition of microglia activation and NLRP3 inflammasome activity." (PMID 36620464, 2022). "The deletion of NLRP3 leads to synaptic transmission impairment, anxiety-like manifestations, and labored fear learning, suggesting an important role of NLRP3-mediated low-level inflammation in memory consolidation." (PMID 35722622, 2022). "Previous studies have also revealed that the activation of NLRP3 plays an important role in different animal models with anxiety-like and depressive-like behaviors." (PMID 36138986, 2022). "NLRP3 KO + alcohol mice spent more time in the center area than WT + alcohol group mice, which indicated less anxiety after binge drinking." (PMID 36539796, 2022). "Recent independent observation from other groups also showed that pharmacological inhibition of NLRP3 using MCC950 reduced anxiety behavior in rodents." (PMID 34895246, 2021). "Because persistent inflammation is implicated as a physiological process in anxiety disorders, we investigated the contributions of NLRP3 inflammasome signaling to anxiety and anxiolytic properties of flavanol diets in a model of chronic sleep deprivation." (PMID 33446652, 2021). "In patients with MDD and anxiety, NLRP3 gene expression is upregulated in peripheral monocytes, while serotonergic anti-depressants downregulate inflammasome gene expression in MDD patients." (PMID 33446652, 2021). "In summary, crocin attenuates LPS-induced anxiety and depressive-like behaviors by suppressing the NF-kB and NLRP3 signaling pathways." (PMID 35003290, 2021). "In rodent models of stress-induced anxiety, activation of the NLR family pyrin domain-containing 3 (NLRP3) inflammasome and upregulation of IL-1β is noted in hippocampal and cortical brain regions and are critical for the onset of anxiety." (PMID 33446652, 2021).
Anxiety (continued). "In the present study, we show chronic sleep deprivation results in increased NLRP3 inflammasome expression, production of cytokines, and markers of microglia activation, accompanying an increase in anxiety phenotypes." (PMID 33446652, 2021). "NLRP3 inflammasome activation correlates with stress responses, depressive- and anxiety-like behaviors, and gut microbiota composition." (PMID 34987395, 2021). "The results of our study suggest that SHD can alleviate cecum mucosal injury and improve depressive- and anxiety-like behaviors by regulating the cecal microbiota and inhibiting the excessive activation of the NLRP3 inflammasome in the cecum and serum." (PMID 34987395, 2021). "Inhibition of NLRP3 with a small molecule inhibitor MCC950 significantly reduced stress-induced anxiety in mice and IL1β as well as Caspase 1 activity." (PMID 34895246, 2021). "The results of these chronic sleep deprivation studies show a critical role of NLRP3 inflammasome signaling and IL-1β production in mouse hippocampus and cortex for the generation of anxiety." (PMID 33446652, 2021). "Genetic knockout of Nlrp3, pharmaceutical inhibition of NLRP3 inflammasome, or IL-1 receptor antagonizing enhanced the extinction of fear memory and attenuated anxiety-like behaviors." (PMID 32635937, 2020). "Our results demonstrate that both genetic knockout and pharmaceutical inhibition of NLRP3 inflammasome remarkably enhance extinction memory and attenuate anxiety-like behaviors." (PMID 32635937, 2020). "Improved extinction learning in Nlrp3 knockout mice has been further proven in the extinction training procedure, as revealed by the significant lower fear response and less anxiety-like behaviors." (PMID 32635937, 2020). "Previous studies also indicated that NLRP3 KO mice displayed decreased anxiety and anhedonic behaviors under basal, unstressed conditions and were resilient to the behavioral deficits caused by CUS exposure." (PMID 31439031, 2019). "This study highlighted that microglial activation is very likely to play a role in CMS-induced depressive- and anxiety-like behavior via NLRP3 inflammasome-IL-1β signaling." (PMID 29343269, 2018). "MLN4924, a potent compound NAE inhibitor in phase 1/2/3 clinical trials for cancers, alleviates psychological stress-induced NLRP3 inflammasome activation, microglia inflammatory activation, and anxiety-like behavior, suggesting novel clinical activity of MLN4924." (PMID 41514502, 2026). "This study revealed that the pharmacological inhibition of the NLRP3 inflammasome not only attenuated the mechanical and thermal allodynia caused by PTX but also the anxiety- and depressive-like behaviors and memory deficits associated with PTX-induced neuropathy." (PMID 40002330, 2025). "Other works have also shown that treatments such as sodium butyrate and ultramicronized palmitoylethanolamide can reduce PTX-induced depressive- and anxiety-like behaviors through inhibiting the expression of several NLRP3-derived proinflammatory cytokines in the brain." (PMID 40002330, 2025). "Similarly, in a traumatic brain injury (TBI) model, genistein alleviated neurological deficits and anxiety-like behaviors by downregulating NLRP3 and caspase-1 expression, suggesting a central role in neuroinflammatory regulation." (PMID 41433336, 2025). "The expression levels of genes such as caspase-1 were significantly downregulated, suggesting that strain WLR01 might alleviate anxiety symptoms in SD mice by suppressing the activation of the NLRP3/caspase-1 pathway." (PMID 39339809, 2024). "In a rodent model of PTSD, hampering the NLRP3 inflammasome reduced anxiety behaviour." (PMID 38421496, 2024). "reuteri WLR01 may reduce the inflammatory response of neural tissue and improve the memory cognitive ability of mice with anxiety-like behavior by inhibiting the NLRP3 inflammatory pathway in the hippocampus." (PMID 39339809, 2024).
Anxiety (continued). "However, it also reduces ROS production and blocks the activation of the NLRP3-Caspase-1 signaling pathway, thus reducing anxiety and stress, so it is recommended to incorporate kidney beans into a routine diet." (PMID 38690099, 2024). "Considering that TNF-α regulates the transcription of the NLRP3 inflammasome, the increased expression of NLRP3 observed in the AMG might also be involved in the anxiety and depressive-like behaviors associated with CCI-induced neuropathic pain." (PMID 37891937, 2023). "Our data show that aging in mice is accompanied by the development of anxiety, impaired social activity, and impaired contextual memory associated with the hippocampus, but not in mice with NLRP3 deletion." (PMID 38068904, 2023). "Based on our present study and the prior literature, we hypothesized the NLRP3 inflammasome activation of microglia in the prefrontal cortex, which promotes anxiety and depressive symptoms in AR." (PMID 38012545, 2023). "NLRP3 knockout mice exhibit changes in anxiety-like behaviors." (PMID 38068904, 2023). "Using optogenetic induction of LTP or LTD, our results showed the relationship between NLRP3 cascade signaling and glutamatergic transmission, providing evidence of NLRP3-mediated regulation in glutamatergic transmission, thereby affecting withdrawal anxiety-like behaviors." (PMID 36539796, 2022). "In the present study, we further emphasize the beneficial effects of FDP treatment in models of stress, finding that administration of FDP to mice subjected to chronic sleep deprivation reduced anxiety by suppressing microglia activation and NLRP3 inflammasome activity." (PMID 33446652, 2021). "In the Dark-Light Box task prior to SD, Nlrp3-/- mice spent significantly more time in the Light Zone and exhibited an increase in voluntary locomotion compared to WT mice, suggesting reduced basal anxiety." (PMID 33446652, 2021). "The results indicated that the SJE could inhibit inflammatory response in the brain of DSS-induced mice by regulating the TLR4/NLRP3 signaling pathway, while suppressing apoptosis and oxidative stress, thereby improving the depressive/anxiety-like behavior." (PMID 34977127, 2021). "We found that Nlrp3−/− could partly inhibit the depressive- and anxiety-like behaviors induced by CUMS." (PMID 34103482, 2021). "To further investigate the role of the NLRP3 inflammasome in SD-associated anxiety, we tested wild-type (WT) C57BL/6J mice and mice lacking the Nlrp3 gene (Nlrp3-/-) for basal anxiety in the Dark-Light Box task." (PMID 33446652, 2021). "Production of IL-1β and NLRP3 were critical for both anxiety phenotypes and microglia activation." (PMID 33446652, 2021). "Although both SHD-H and FOS can remodel cecal microbiota dysbiosis, SHD-H has more obvious advantages in maintaining weight gain, improving cecum mucosal injury, reversing depressive- and anxiety-like behaviors, and regulating NLRP3 inflammasome expression in CUS model rats." (PMID 34987395, 2021). "It is indicated that Nlrp3−/− could partly inhibit the depressive- and anxiety-like behaviors induced by CUMS." (PMID 34103482, 2021). "The intestinal microbiota and NLRP3 inflammasome are involved in the development of depression, anxiety, and functional gastrointestinal disorders that are induced by chronic stress; thus, they are recognized as potential targets for managing stress-related diseases." (PMID 34987395, 2021). "Here, we show that mice deficient in inflammasome regulators, including caspase-1 (Casp1), NLR family pyrin domain containing 3 (Nlrp3), IL-1 receptor (Il-1r), and gasdermin D (Gsdmd), exhibit behavior abnormalities characterized by hyperactivity and low anxiety levels." (PMID 33414187, 2021). "Notably, Nlrp3−/− mice displayed significant attenuated anxiety-like behavioral preference induced by foot shocks, as evidenced by significant higher entries, time spent, and distance traveled at open arms compared with WT mice (t test, p < 0.01)." (PMID 32635937, 2020).
Anxiety (continued). "In the OF test, Nlrp3-/- mice displayed significantly attenuated anxiety-like behavioral preference induced by foot shock, as evidenced by significant higher entries, time spent, and distance traveled at the center area observed in knockout mice than in WT mice (t test, p < 0.01)." (PMID 32635937, 2020). "In vivo, WLBA3 reduced inflammation and oxidative stress by inhibiting the NLRP3 inflammasome pathway and modulating gut microbiota (e.g., Lactobacillus and Alistipes), which in turn significantly improved weight gain and fatigue resistance, attenuated cognitive function, and anxiety-like behavior." (PMID 41982656, 2025). "Furthermore, MLT might be effective against chronic NP-mediated anxiety- and depressive-like behaviors by regulating Bax/Bcl2 and NF-κB/NLRP3 signaling pathways in the PFC and HC." (PMID 36747075, 2023). "Thus, molecules that inhibit NLRP3 pathways and reduce the levels of pro-inflammatory cytokines may be a promising strategy for the development of anti-anxiety drugs." (PMID 35203954, 2022). "Interestingly, NLRP3 deficiency or inhibition (MCC950 injection) attenuated the anxiety-like behavior, but it did not prevent DID + gavage paradigm-induced a persistent enhancement of drinking in a two-bottle choice at 2 and 4 days into withdrawal." (PMID 36539796, 2022). "However, whether and how inhibition of the NLRP3 inflammasome alters alcohol intake and anxiety behavior remains unclear." (PMID 36539796, 2022). "Our in vivo study clearly demonstrated that Tojapride effectively ameliorated modified RE rat anxiety‐related behaviour, prevented reflux of gastric and duodenal contents, diminished the pathological impairment and inhibited the proinflammatory pathway of the CaSR/NLRP3 inflammasome." (PMID 31859410, 2020). "We also detected an increase of NLRP3 inflammasome and some inflammatory mediators in the hippocampus after chronic stress and found that minocycline treatment can alleviate the depressive- and anxiety-like behavior and neuro-inflammation induced by chronic stress." (PMID 29343269, 2018). "Moreover, inhibition of the NLRP3 inflammasome activation could reduce hippocampal IL-1β expression level and obviously improved the anxiety- and depressive-like behaviors in mice." (PMID 29495433, 2018). "Treatment with 1m, 1a, 1b, or DMF normalized the NLRP3 up-regulation provoked by CCI in the AMG and inhibited the anxiety- and depressive-like behaviors related to neuropathic pain." (PMID 37891937, 2023). "There is now also evidence that upregulation of the NLRP3 inflammasome plays a key role in MDD, fatigue, cognitive impairments, and anxiety." (PMID 36675440, 2023). "The observation that Nlrp3-/- mice do not exhibit anxiety phenotypes following sleep deprivation support that FDP metabolites reduced IL-1β in sleep deprivation models by inhibiting the NLRP3 inflammasome." (PMID 33446652, 2021). "As individual metabolites derived from FDP inhibited IL-1β production and NLRP3-deficit mice show suppressed anxiety in response to chronic sleep deprivation, this supports the conclusion that anxiolytic effects of FDP were in part due to suppressed NLRP3 activity." (PMID 33446652, 2021). "Thus, NLRP3−/− has a protective genotype during aging in terms of signaling memory and social patterns, but not in anxiety-like behavior." (PMID 38068904, 2023).
non-alcoholic steatohepatitis (87 papers, 2013 to 2026). "While NLRP3 inflammasome components are minimally expressed in healthy hepatocytes, their significant growth is observed in human metabolic dysfunction-associated steatohepatitis (MASH)." (PMID 39512967, 2024). "Erysipelotrichia has been associated with nonalcoholic steatohepatitis, the pathophysiology of which involves the NLRP3 and NLRP6 inflammasomes." (PMID 33414380, 2021). "The NLRP3 inflammasome has been implicated in pathogenesis of many chronic liver diseases, including viral hepatitis, non-alcoholic steatohepatitis (NASH) and alcoholic liver disease." (PMID 32192118, 2020). "Among these, NLRP3 inflammasome has been implicated in both alcoholic and non-alcoholic steatohepatitis." (PMID 31547621, 2019). "NOD-like receptor (NLR) NLRP3 inflammasome activation has been implicated in the progression of non-alcoholic fatty liver disease (NAFLD) from non-alcoholic fatty liver (NAFL) to non-alcoholic steatohepatitis (NASH)." (PMID 28499273, 2017). "NLRP3 inflammasome activation has also been definitively ascribed as a molecular cause of non-alcoholic fatty liver disease (NAFLD) to non-alcoholic steatohepatitis (NASH) progression—a major and rapidly increasing primary etiology for eventual liver transplant recipients." (PMID 34639062, 2021). "In addition, development of nonalcoholic steatohepatitis (NASH) is linked to the impaired mitophagy leading to hepatic NLRP3 inflammasome activation." (PMID 32630319, 2020). "Berberine inhibited hepatic necroinflammation, IL-1β, and NLRP3 inflammasome in non-alcoholic steatohepatitis (NASH) induced by methionine and choline - deficient diet in mouse, which based on interference with activation of P2x7, a purinergic receptor involved in inflammasome activation." (PMID 29922155, 2018). "It has also been reported that ER stress activates NLRP3 inflammasomes in HCs, leading to liver injury, inducing fever and cell death, and contributing to non-alcoholic steatohepatitis." (PMID 40089787, 2025). "In methionine‐choline‐deficient high‐fat diet‐induced nonalcoholic steatohepatitis (NASH), paeoniflorin reduces inflammation by inhibiting the NLRP3 inflammasome and activating the AhR pathway." (PMID 39568773, 2024). "The evidence indicates that melatonin inhibits the activation of NLRP3 inflammasome in a mouse model of non-alcoholic steatohepatitis induced by high fat diet by inhibiting P2X7R receptors." (PMID 37153780, 2023). "Chen and colleagues established the formation and activation of the NLRP3 inflammasome and IL-1β in nonalcoholic steatohepatitis." (PMID 37568105, 2023). "ROS trigger the NLRP3 inflammasome activation and contribute to nonalcoholic steatohepatitis (NASH) progression." (PMID 37859981, 2023). "Several liver-related inflammatory diseases, especially chronic hepatitis C, nonalcoholic steatohepatitis, alcoholic liver disease, and IDILI have been reported to be associated with NLRP3 inflammasome activation." (PMID 36386137, 2022). "Specifically, microvesicles released from fat-laden liver cells promoted the activation of the NLRP3 inflammasome, with a pro-inflammatory link between lipotoxicity and non-alcoholic steatohepatitis." (PMID 32977490, 2020). "Increasing evidence has demonstrated that Nod-like receptor family pyrin domain containing 3 (NLRP3) inflammasome activation and the subsequent pyroptosis contribute to the progression of non-alcoholic steatohepatitis (NASH)." (PMID 32194416, 2020). "Recently, the combination of CHOP-induced apoptosis and NLRP3 inflammasome-mediated pyroptosis has been demonstrated to be involved in the pathogenesis of experimental non-alcoholic steatohepatitis, which was successfully counteracted by treatment with TUDCA." (PMID 28117681, 2017). "Indeed, LPS alone can induce NLRP3 inflammasome activation in mouse primary hepatocytes and in a non-alcoholic steatohepatitis mouse model." (PMID 41590661, 2026).